CRIPT (CXXC repeat containing interactor of PDZ3 domain)
Description:
As a component of the minor spliceosome, involved in the splicing of U12-type introns in pre-mRNAs (Probable). Involved in the cytoskeletal anchoring of DLG4 in excitatory synapses (By similarity).
Synonyms: HSPC139; RTS3; SSMDF
Tractability: Small molecule: a structure with a bound ligand is known. PROTAC: ubiquitination databases record sites on it.
Gene: Protein-coding gene on chromosome 2 (46,616,416 to 46,685,037, forward strand). Ensembl gene ENSG00000119878.
Subcellular location: Cytoplasm; Synapse; Cell projection, dendritic spine
Subcellular location (Human Protein Atlas): Nucleoli fibrillar center; Nucleoplasm
Gene Ontology:
Molecular function: PDZ domain binding; protein binding; scaffold protein binding; microtubule binding; protein-containing complex binding
Biological process: cytoplasmic microtubule organization; mRNA splicing, via spliceosome; protein localization to microtubule; regulation of postsynaptic density protein 95 clustering; regulation of postsynaptic density assembly
Cellular component: U12-type catalytic step 2 spliceosome; dendrite; dendritic shaft; dendritic spine; neuronal cell body; postsynaptic density; cytoplasm; glutamatergic synapse; postsynaptic density, intracellular component; synapse
Genetic constraint (gnomAD): Loss-of-function variants: 1 observed, 1.38 expected, observed/expected ratio (o/e) 0.73, 90% interval 0.22 to 1.85. That is too few expected variants to judge how well the gene tolerates losing a copy. Missense variants: 7 observed, 3.9 expected, observed/expected ratio (o/e) 1.79, 90% interval 0.89 to 1.95. Synonymous variants: 2 observed, 1.13 expected, observed/expected ratio (o/e) 1.77, 90% interval 0.5 to 1.93.
Homologues: Orthologues: chimpanzee CRIPT (100% identical), guinea pig CRIPT (100% identical), rabbit CRIPT (100% identical), mouse Cript (99% identical), rat Cript (99% identical), macaque CRIPT (95% identical), zebrafish cript (93% identical), tropical clawed frog cript (92% identical), dog CRIPT (68% identical), Drosophila melanogaster CG4537 (60% identical), Caenorhabditis elegans C36B1.14 (45% identical). Paralogues in human: POLR1C (26% identical), POLR2C (20% identical).
Diseases named in the same sentence as CRIPT in open-access papers:
CRIPT is named in the same sentence as 9 diseases in open-access papers, as found by Europe PMC text mining. Sharing a sentence is not in itself a finding about the gene and the disease. The quoted sentences say what the papers report.
developmental delay (2 papers, 2017 to 2023). "Neurological involvement, as either developmental delay/intellectual disability, or the presence of seizures, were most common in the individuals harboring CRIPT biallelic variants, while microcephaly is most frequent in both CRIPT and DNA2 patients." (PMID 38021400, 2023).
primordial dwarfism (1 paper, 2023). "The first reports of individuals harboring biallelic variants in DNA2 and CRIPT were identified in cohorts of individuals with a clinical diagnosis of primordial dwarfism." (PMID 38021400, 2023).
CRIPT also shares sentences with these, for which no sentence is quoted: genetic disorders (1 paper); infection (1); Intellectual disability (1); Kindler syndrome (1); microcephaly (1); neutropenia (1); Rothmund-Thomson syndrome (1).